ERBB2 (erb-b2 receptor tyrosine kinase 2)
Diseases named in the same sentence as ERBB2 in open-access papers (continued):
Sharing a sentence is not in itself a finding about the gene and the disease.
tumor (continued). "In the MBC population of the patients, one actionable mutation—PIK3CA, ESR1, ERBB2, or AKT1—was found in ten patients and two in three cases either in the tumor or in the plasma." (PMID 34298704, 2021). "Nuclear expression of ErbB2 and other EGFRs is mainly found in tumor cells but also in proliferating cells during embryonal development." (PMID 32591879, 2021). "It should be noted that almost 39% of tumor samples from patients with untreated SCCHN had overexpression of ErbB2/HER2, which suggests that it can serve as a possible target for therapy." (PMID 34298761, 2021). "The tumor phenotype of most cases was ER+ (n=37, 97.4%), followed by RP (n=34, 87.2%), and c-erbB2/HER2 (26.3%)." (PMID 33639684, 2021). "In HER2 positive BC, a heterogeneous HER2 immunohistochemical staining and ERBB2 gene amplification evaluated by FISH have been associated with shorter survival and tumor progression." (PMID 34573897, 2021). "The present study has assessed the role of the LXR agonist DMHCA in reducing tumorigenesis and ameliorating fibrosis and immune tolerance in the NeuT/ATTAC fibrosis model of ErbB2 neoplasia." (PMID 33780491, 2021). "This study focused on the effects of the drug Tz on EVs released from ERBB2+ (BCa) cells using widely used cell lines derived from this tumor type and found that Tz indeed modulates the composition of proteins carried by EVs." (PMID 33809102, 2021). "Infigratinib-resistant tumours exhibited higher levels of p-ErbB2 and p-ErbB3, concomitant with an increase in EZH2 expression." (PMID 34156519, 2021). "In cancer, uncontrolled tumor growth is led by gene amplification and overexpression of ErbB2 and ligand-independent ErbB2-ErbB3 heterodimer complex." (PMID 34638281, 2021). "The HER2-Enriched (HER2-E) subtype according to PAM50 is defined by higher expression of ERBB2 along with the upregulated expression of tumor proliferation-related genes at the RNA and protein levels in comparison to other cancer types." (PMID 34681026, 2021). "KIF11 likely promotes tumor cell mitosis and cell proliferation through ERBB2/PI3K/AKT signaling pathway." (PMID 33613109, 2021). "CD73 blockade enhances the anti-tumor activity of the anti-ErbB2 antibody against engrafted or spontaneous tumors, as well as lung metastases." (PMID 33430239, 2021). "NF-κB signaling has been shown to enhance ErbB2-induced tumor growth both in vitro and in immune-competent mice." (PMID 33785053, 2021). "Circ-ERBB2, also named hsa_circ_0043459, has attracted our attention due to its function in tumor regulation." (PMID 34732216, 2021). "In contrast to the strong membrane staining seen in MMTV-Neu tumours, ERBB2 staining in BlgCre-NeuKI tumours was weak and typically cytoplasmic, with weak membrane staining in fewer than half of all cases." (PMID 34003256, 2021). "THC treatment, in a mouse model of ErbB2-driven metastatic breast cancer, decreased tumor proliferation, as well as lung metastases." (PMID 33916164, 2021). "Use of positivity thresholds for detection of each marker by IHC (and for detection of ERBB2/HER2 amplification by fluorescence in situ hybridization) identifies four tumor subtypes, ER+HER2−, ER+HER2+, ER−HER2+ and ER−HER2−." (PMID 34831189, 2021). "Studies found that integrin β4 promotes prostate tumorigenesis by co-expressing with ErbB2 and c-Met in tumor progenitor cells." (PMID 34439865, 2021). "Overall, our findings reinforce previous studies describing that the inhibition of both BRD4 and the ERBB2 downstream PI3K pathway produces antitumoral activity in different tumor cell lines." (PMID 33741018, 2021).
tumor (continued). "Gene amplification (e.g., EGFR, TERT, MYC, and ERBB2) was identified in tumor samples from 10 patients but was present only in paired tumors for one patient." (PMID 34109114, 2021). "In general, activation of the CNN-based ERBB2 predictor was focused on tumor epithelium, and larger and smaller nests of malignant epithelial cells, rather than stromal areas." (PMID 33597560, 2021). "ERBB2-positive p140Cap tumor cells show a significant decrease in the activation of Tiam1 and of Rac." (PMID 33079227, 2021). "Genomic studies in almost all types of human tumors show aberrations in several RTKs associated with tumor development and progression such as EGFR, HER2/ErbB2, MET, etc.." (PMID 33918490, 2021). "Western blot analyses of tumor tissue lysates from Rlip+/+, Rlip+/− and Rlip−/− genotypes of the Erbb2 and PyVT GEM models revealed significant differences in the patterns of signaling proteins." (PMID 34283045, 2021). "For example, ERBB2 was shown to play a role in the progression of PC through an increase in angiogenesis, thereby facilitating the dissemination of tumor cells." (PMID 33918389, 2021). "ST6GAL1 endows resistance of cancer cells to gefitinib (EGFR inhibitor) and trastuzumab (anti-ErbB2 antibody) and also confers tumor cell resistance against hypoxia via enhancing hypoxia-inducible factor-1α (HIF-1α) expression." (PMID 34745942, 2021). "Here, the authors profile AFPGC tumours using whole exome sequencing, and find amplifications in CCNE1 and ERBB2 that are associated with poor outcomes but are potential therapeutic targets, as shown in patient-derived xenografts." (PMID 34168152, 2021). "Nineteen percent of tumour samples from HNSCC patients are ErbB2 positive, favouring attempts to further use Lapatinib in studies." (PMID 34944837, 2021). "The significant depletion of HER2 in the mesenchymal-like cells inside the tumor can take place by chromatin-based epigenetic silencing of the ERBB2 gene during EMT." (PMID 34575017, 2021). "Clinically, the anti-tumor activities of anti-HER2 (often referred to as ErbB2) therapies, with trastuzumab being the most recognized, are attributed to more than a single mechanism of action." (PMID 34358100, 2021). "The third tumor, PS13-585, was a large node positive tumor (pT2, pN3c, pMX) with a diagnosis based on a single core needle biopsy of grade 3 ER+ PR− ERBB2+ (3+)." (PMID 34011996, 2021). "Tumours were considered as luminal type if they had a high expression of ERBB2, ESR1, or KRT20 while showing a low expression of KRT5." (PMID 34073233, 2021). "Because ACP, which is considered a benign tumor, carries a low rate of somatic mutations, mounting evidence suggests that the TGF-β, ERBB2 and SHH signaling pathways are involved in tumor formation in an autocrine or paracrine manner." (PMID 35155179, 2021). "BXL0124 decreased tumor weight, incidence, and multiplicity and inhibited ErbB2, Erk, and Akt signaling." (PMID 34950835, 2021). "Intensive research on EGFR I and ErbB2 in tumor cells has led to successful therapeutic strategies targeting these receptors: Anti-EGFR molecules like cetuximab or gefitinib are used in colorectal cancer, lung cancer, head and neck carcinoma, and others." (PMID 32591879, 2021). "We also checked the transcriptional levels of ER genes, PR genes, and HER2 (Erbb2) and found rare transcripts in the cancer cells of all the tumor models, even in the NEU model, suggesting that these were good models to mimic TNBC." (PMID 34497807, 2021). "After the patient was treated with gefitinib initiation (250 mg/d) for 15 months, the tumor progressed with ERBB2 amplification revealed by next-generation sequencing test." (PMID 33663050, 2021).
tumor (continued). "In contrast to unmodified parental NK-92 cells, which failed to lyse RMS cells, NK-92/5.28.z cells proliferated and became further activated through contact with ERBB2-positive tumor cells." (PMID 33809981, 2021). "In comparison with the Lenti-sh-NC group, the circ-ERBB2 knockdown reduced the tumor volume and weight." (PMID 34732216, 2021). "Preclinical study demonstrated that CAR-NK cells targeting specific antigens linked to CSCs (e.g., GD2, EGFRvIII, ErbB2, CD133, PSCA) displayed superior anti-tumor activity compared to parallel-unmodified NK cells." (PMID 33806296, 2021). "We conclude Pparγ1 promotes ErbB2-induced tumor growth and inflammation and represents a relevant target for therapeutic coextinction." (PMID 33946495, 2021). "NIH 3T3 fibroblasts expressing oncogenic human ErbB2 treated with NK-92- ErbB2 targeting CAR cells resulted in a reduction in tumour growth in a xenograft model compared to tumours treated with unmodified NK-92." (PMID 33923528, 2021). "In this study, we employed ERBB2-CAR-modified NK-92 cells (NK-92/5.28.z), which are already available as a GMP-compliant product, as effector cells against high-risk aRMS tumor cells." (PMID 33809981, 2021). "Altogether, NK-92/5.28.z cells demonstrated significantly increased lysis of ERBB2-positive tumor cells compared to NK-92 cells, even at an E:T ratio of 5:1." (PMID 33809981, 2021). "Further, we detected activating mutations in KRAS, ERBB2, RET, and CTNNB1, presumably conferring a new oncogenic driver in the respective tumor." (PMID 34201252, 2021). "Genomic characteristics, such as the oncogene activation (e.g., ERBB2 amplification, EGFR tyrosine kinase mutation) and inactivation of tumor suppressor genes (e.g., MMR, BRCA1/2) have shown a strong correlation with clinical response to target therapy." (PMID 34047476, 2021). "These NK-92/5.28.z cells displayed high and specific activity against ERBB2-positive cancer cells, serial target cell killing, and homing to distant tumor sites in preclinical models of cancers of different solid tumor origins." (PMID 33809981, 2021). "Tumours collected from mice at diestrus exhibited a significant increase in the expression of genes Mki67 (p = 0.05), Ccnb1 (p = 0.02), Erbb2 (p = 0.03), Grb7 (p = 0.02), and Bag1 (p = 0.05), compared to tumours collected at estrus." (PMID 34174867, 2021). "As tumours progress to become more aggressive and metastatic, Erbb2 and Ccnd1 increase in expression." (PMID 34174867, 2021). "In this line, the genetically modified NK-92-scFv (FRP5)-zeta cells showed a great promise in killing the several types of ErbB2-expressing tumor cells and introduced as a new therapeutic solution for the treatment of ErbB2-expressing tumors." (PMID 33752707, 2021). "UroC also represents a further progressed variant of UroA with a similar expression of FGFR3, although it also resembles GU tumor subtype in terms of ERBB2 expression." (PMID 34771699, 2021). "The expression of PCNA in the INT and IT groups were detected in the nucleus of tumor cells (respectively), while the expression of ErbB2 in both groups was found on the cell membranes (respectively)." (PMID 34164110, 2021). "An ErbB2-driven breast cancer mouse model (MMTV/Neu) also responded to lapatinib treatment with increased IFNγ driven anti-tumor adaptive immune responses in a STAT1 dependent manner." (PMID 33807608, 2021). "Tumours with an elevated expression of markers associated with luminal differentiation (KRT20, ERBB2, ESR1) were associated with a higher chance of pCR (55% vs. 15.8%, p = 0.009)." (PMID 34073233, 2021). "Western blots were performed to evaluate the expression of BRD4 and ERBB2 in tumor lysates at the end of treatment." (PMID 33741018, 2021). "As well as trastuzumab, pertuzumab disrupts ErbB2 dimerization and involves the immune system to fight tumor." (PMID 34944558, 2021).
tumor (continued). "Five mutations in PIK3CA, one in BRCA1 and one in IDH1 found in this study are FDA-recognized biomarkers (level 1) and one ERBB2 mutation is a standard care biomarker (level 2A), predictive of response to FDA-approved drugs in specific tumor types." (PMID 33500480, 2021). "All aRMS tumor cell suspensions displayed low but homogenous ERBB2 expression (RH30, MFI 3.6 ± 0.0, n = 3; RH41, MFI 1.7 ± 0.1, n = 3; primary aRMS cells, MFI 1.9, n = 1)." (PMID 33809981, 2021). "Descriptive genomic analysis of pre-NAC tumor samples identified mutations in ERBB2 and DNA repair genes; ATM, RB1, FANCC, and ERCC2 were associated with tumor response to NAC." (PMID 33799514, 2021). "Similar findings of PDPK1 promoting tumor initiation in cooperation with Erbb2 or Ras activation have been made in breast cancer cells, or in BRAF V600 mutant melanoma where loss of PDPK1 reduced tumor formation." (PMID 34079928, 2021). "In cytotoxicity assays, NK-92/5.28.z cells specifically recognized and efficiently eliminated RMS cell suspensions, tumor cell monolayers, and 3D tumor spheroids via the ERBB2-CAR even at effector-to-target ratios as low as 1:1." (PMID 33809981, 2021). "Here, we addressed the pro-tumoral role of CD151 in NSCLC by targeting EGFR/ErbB2 which favors tumor proliferation, migration and invasion." (PMID 34108040, 2021). "Although some are still under investigation, many studies have shown that these ERBB2-targeting techniques not only inhibit tumor growth, but also lead to chemo-sensitization of ERBB2-overexpressing cancer cells." (PMID 34259866, 2021). "ERBB2 was identified as an outlier gene in three tumor sample sets from three urothelial cancer patients in our cohort." (PMID 34385467, 2021). "In fact, ErbB2 can dimerize with other ErbB receptors expressed by tumor cells, thus conferring a proliferative advantage of cells over homodimerization-induced growth." (PMID 34561494, 2021). "Overwhelming evidence from numerous studies indicates that amplification or overexpression of ERBB2 disrupts normal cell control mechanisms and gives rise to aggressive tumor cells." (PMID 34259866, 2021). "The significant delay in tumor formation in the Erbb2 mouse model by Rlip depletion has significant implications of its own." (PMID 34283045, 2021). "Tumours collected from mice at diestrus showed a significant increase in the expression of Erbb2 compared to tumours collected from mice at estrus (p = 0.03)." (PMID 34174867, 2021). "The loss of oncogenic RAS and SMAD4 signals synergistically upregulate the abnormal expression of EGFR and ERBB2, leading to the development of neoplasm and the metastasis and spread of the primary tumor." (PMID 34301194, 2021). "A nude mouse xenograft model was used to examine the effects of the Cdc25A/ErbB2 axis on tumour growth in vivo." (PMID 34743185, 2021). "In the case of CD151, a series of in vitro and in vivo studies reveal a strong inhibitory effect of CD151 downregulation or deletion on tumor onset and growth in either ErbB2+ or basal-like subtypes." (PMID 33919420, 2021). "ERBB2 mRNA expression was assessed in 77 tumor samples from patients with advanced HER2+ BC treated with T-DM1." (PMID 32674482, 2020). "ErbB2 is a receptor tyrosine kinase regulating key tumor cell characteristics, which induces survival, proliferation, and migration." (PMID 32679791, 2020). "NRAS, FGFR2, and ERBB2 have been associated to CDK4/6i resistance and/or antiestrogen resistance in whole exome analysis of tumor specimens." (PMID 32899866, 2020).
tumor (continued). "By utilizing the tyrosine kinase inhibitors (e.g., gefitinib and erlotinib) or monoclonal antibodies (e.g., cetuximab and trastuzumab), they can inhibit the activities of EGFR/ERBB2 to effectively suppress the tumor cell growth." (PMID 33287876, 2020). "A breakthrough inantitumor therapy occurred with the advent of the drug Herceptin (trastuzumab),which is a humanized antibody to the extracellular domain of ErbB2,which inhibits the proliferation of tumor cells." (PMID 32742732, 2020). "Patients with high ERBB2 expression are prone to tumor metastasis and have a short survival period, which has become an ideal target of tumor immunobiotherapy and a hot molecule in the field of tumor therapy." (PMID 32963562, 2020). "Previously, NER monotherapy in neoadjuvant settings has been shown to inhibit tumor growth and metastasis in the ERBB2+ orthotopic model of spontaneous metastasis." (PMID 33019652, 2020). "Subgroup analyses were performed based on sex, race, adjusted AJCC sixth edition stage, tumor grade, histology type, and ERBB2 status (eFigures 1-6 in the Supplement)." (PMID 31899528, 2020). "Several studies found that the epidermal growth factor receptor (EGFR) family, particularly ERBB2 (a member of this family), was involved in alcohol-mediated tumor promotion." (PMID 33203443, 2020). "Despite the fact that PI3K/Akt signaling is a primary pathway for tumor development, in ER-negative/ERBB2-positive BC cells, ERBB2 has been shown to stimulate NF-kB through the canonical pathway independently of the PI3K axis." (PMID 33066388, 2020). "Due to ErbB2 and ErbB3 mutations at a frequency of 7–8% in GBC, ErbB2/ErbB3 mutation inducing PD-L1 overexpression can mediate immune escape of tumor cells via PI3K/AKT pathway in vitro." (PMID 32333246, 2020). "In this study, we reported an orthotopic model of spontaneous ERBB2+ BC BrM that can be used to evaluate therapeutic approaches targeting both the primary tumor and distant metastases together, suggesting its high clinical relevance." (PMID 33019652, 2020). "As for locoregional radiotherapy alone, ERBB2 positivity and larger tumor size were identified as the independent prognosticators of both inferior survival and recurrence outcomes." (PMID 32644137, 2020). "The same TERT mutation present in tumors 2–3 remained present in the progression tumor, but the inferred ERBB2 amplification status changed." (PMID 31609466, 2020). "We conclude that though miR-125a-3p induces ErbB2 expression, it suppresses the downstream signaling pathways, reducing the migratory capability of the cells and acting as a tumor suppressor miRNA in MDA-MB-231 cells." (PMID 32185126, 2020). "Very recently, a ERBB2-retargeted oHSV armed with IL-12 proved to be efficacious in subcutaneous and glioblastoma tumour models." (PMID 32152425, 2020). "Based on the results that emerged, we propose the use of these drugs in the treatment of patients with BRAF-mutant CRCs, based on the tumor’s expression of ErbB2." (PMID 32066410, 2020). "The combination of the additional ERBB2 retargeting further improved the selectivity for tumour cells, conferring to the double regulated virus a very limited ability to infect and propagate in non-cancerous cells." (PMID 32152425, 2020). "ERBB2/HER2 overexpression was identified in very aggressive primary tumours and metastatic lesions of EC, mostly in the serous subtype, suggesting that these changes induce AKT phosphorylation." (PMID 32842533, 2020). "Consistent with results from HCC1954 xenograft study, the combined treatment with ML364 and 17-AAG displayed the strongest suppression against xenograft tumor growth, which was accompanied with potent ErbB2 downregulation." (PMID 32327714, 2020).